TIMP1 (TIMP metallopeptidase inhibitor 1)
Diseases named in the same sentence as TIMP1 in open-access papers (continued):
Sharing a sentence is not in itself a finding about the gene and the disease.
cancer (continued). "Decreased hyaluronan synthesis due to knockdown of HAS2 probably explains some of the anti-tumorigenic effects, but HAS2 might harbor some other mechanisms too such as regulating TGFβ-induced epithelial-mesenchymal transition or increasing cancer cell invasion by downregulation of TIMP-1." (PMID 29914429, 2018). "TIMP-1 overrides MMP-9 activity in cancer and might be regulated by miR-618." (PMID 30340564, 2018). "For multiple cancers, it has been shown that high TIMP-1 levels in blood are associated with unfavorable prognosis and a decrease in progression-free survival yet it has not been established as a viable biomarker for cancer." (PMID 29507665, 2018). "Similarly, in solid tumors, TIMP-1 improves the metastatic potential of cancer cells." (PMID 27903985, 2017). "Moreover, TIMP-1 has been shown to be involved in cancer progression." (PMID 27903985, 2017). "The roles of TIMP-1 and TIMP 2 (both are inhibitors of matrix metalloproeteinases) in MDSC generation are less clear, though serum TIMP-1 levels are associated with shorter survival in many types of cancer and TIMP-2 has been shown to be a negative regulator of MDSCs in mice." (PMID 28666020, 2017). "MMP-7 and TIMP-1 may play a role in the pathogenesis of cancer disease." (PMID 28662671, 2017). "Our conclusion is that TIMP1 may be acting in a less benign way, analogous to its role in cancer." (PMID 23555662, 2013). "However, it is unclear whether TIMP-1 serves merely as a biomarker of cancer progression or functions to promote cancer progression as well; and thus could serve as an important cancer therapeutic target." (PMID 24143225, 2013). "However, it is still unknown whether TIMP-1 serves merely as a biomarker of cancer progression or functions to promote cancer progression." (PMID 24143225, 2013). "However, it is unknown whether TIMP-1 serves merely as a biomarker of cancer progression or has a functional role in promoting cancer progression and can serve as a cancer therapeutic target, which is the main objective of this study." (PMID 24143225, 2013). "The group in which cancer cells were treated with 4000 EVs per cell showed a decrease in MMP9 and TIMP1 gene expressions, whereas the group with 12,000 EVs per cell showed no significant change." (PMID 40208413, 2025). "Our analysis revealed a complex interaction between TIMP1 and MMP10, suggesting their pivotal roles as central nodes in both coagulation and cancer pathways." (PMID 40777024, 2025). "According to pathway enrichment analysis, both PMEPA1 and TIMP1 primarily affect cytokine activity and the classic WNT signaling pathway, playing a crucial role in cancer development." (PMID 40244296, 2025). "Previous research has shown that CBD can increase the expression of Timp1, supporting the protection of the ECM against degradation and potentially benefiting the treatment of inflammation and cancer." (PMID 40335839, 2025). "qRT-PCR analysis showed that the mRNA expression levels of TIMP1, CDC25C, ATP2A1, and TIGD1 were upregulated in cancer cell lines compared to normal cell lines, whereas NRG1 and DMPK exhibited reduced expression in cancer cell lines." (PMID 41190067, 2025). "With regard to proteins released after sonication, several molecules were identified as candidate biomarkers in cancer US supernatants (Beta-2 microglobulin, CA125, CA19-9, CEA, CRP, Galectin-3, TIMP-1, uPA, and VEGF-A)." (PMID 40563629, 2025). "Key hub genes including CD68 in BRCA, CD74 in CRC and OVCA, and TIMP1 in LUSC, played critical roles in immune-cancer cell interactions and tumorigenesis inhibition." (PMID 41370198, 2025). "MMP-8 and TIMP-1 have prognostic significance in several cancers, but it has also been reported that MMP-8 has distinct roles in different cancers." (PMID 39917664, 2024). "Herein we show that at the RNA level, TIMP1 expression does correlate with CD8A expression in the TME of several cancer types of the PANCAN study, extending its pro-inflammatory roles in cancer." (PMID 38777826, 2024).
cancer (continued). "By binding to these MMPs, TIMP-1 inhibits their proteolytic activity, thereby reducing ECM degradation and potentially hindering cancer cell invasion and metastasis." (PMID 39199626, 2024). "CCX832 inhibits these effects by downregulating tissue inhibitors of metalloproteinases (TIMP-1 and TIMP-2), highlighting chemerin’s role in enhancing cancer cell invasiveness." (PMID 39590835, 2024). "Taken together, these data give new insights into the complex nature of TIMP‐1 and they can aid in explaining so far unresolved functions of TIMP‐1 with specific emphasis on cancer progression." (PMID 37081824, 2023). "For example, Metalloproteinase Inhibitor 1 (TIMP-1) inhibits Interstitial collagenase (MMP-1) canonically, but its moonlighting function activates cell proliferation and survival in cancer." (PMID 36672169, 2023). "This work attempts to comprehensively describe the changes in gene expression of gelatinases and TIMP1 in NSCLC, as a result of cancer development and progression as well as a consequence of applied treatment." (PMID 37509417, 2023). "We confirmed HCC by analyzing Western blot of the expression of cancer markers—MCP-1, TIMP-1, and GP3—in either isolated nodules from HCV-infected mice or from liver tissue from uninfected mice." (PMID 37896876, 2023). "TIMP-1 can also act as a signaling molecule on the cell surface receptor CD63, activating downstream signaling pathways and paving the way for cancer pathogenesis." (PMID 37629569, 2023). "TIMP1 has been reported to promote cell proliferation in TNBC and can modulate the radiosensitivity of cancer cells based on its enzymatic inhibition characteristics." (PMID 36681663, 2023). "On the other hand, CCL11 (Eotaxin), HGF, TIMP‐1 and MCP‐1 (CCL2) were secreted more by the fibroblasts compared to prostate epithelial/cancer cells." (PMID 36608258, 2023). "Extravesicular TIMP-1 activity was extensively investigated in stromal fibroblasts, which induced TIMP-1 release by fibroblasts, as well as ECM remodelling and cancer invasion." (PMID 38069076, 2023). "In lung adenocarcinoma, it was demonstrated that SMAD3/TIMP-1 in CAFs and CD63 in cancer cells were necessary to drive tumour progression in vitro and in vivo." (PMID 36555218, 2022). "Crucially, TIMP-1 inhibits collagen-degrading enzymes such as matrix metalloproteinase (MMP)-2 and MMP-9, which play an important role in promoting cancer metastasis." (PMID 35277658, 2022). "Numerous studies have reported that MMP-1, MMP-2, and MMP-9 enzymes and TIMP-1 and TIMP-2 inhibitors play an active role in angiogenesis, local invasiveness, and metastatic potential of malignant tumors." (PMID 36551933, 2022). "TIMP1 is a member of the TIMP family with multiple functions, and its role in cancer has been controversial." (PMID 36439446, 2022). "From heatmap analyses, it was observed that all of these protein-coding hub genes were up-regulated in the case of Ponatinib-resistant cancer and only FN1, CD44 and TIMP1 were up-regulated in Foretinib-resistant cancer." (PMID 35534592, 2022). "The study identified FN1, CD44, TIMP1, SPARC and SNAI2 as common coding hub proteins for most of the drug-resistant cancer types." (PMID 35534592, 2022). "TIMP1 is matrix metalloproteinase (MMP)-independent and regulates cell development and apoptosis in various cancer cell types, including CRC." (PMID 34440739, 2021). "Many explanations exist for this contradictory phenomenon, such as the interaction between TIMP1 and CD63 to activate MAPK signalling and participation in the HGF/c-Met pathway to promote cancer progression." (PMID 34781885, 2021). "These two targets have a few interacting proteins in common such as TIMP (1, 2 and 3), STAT 3, VEGF A, SRC, DCN, MMP 10 and CD 44 and all are supposed to be plum targets for cancer therapies." (PMID 34075089, 2021).
cancer (continued). "Compared with the expression levels in normal samples, ITLN1, TSPAN11, CPRC5B, and CXCL13 showed significantly low expression levels in most cancer types, including COAD, while TIMP1 was expressed highly in most cancer types." (PMID 33579281, 2021). "Indeed, B7-H3 was implicated in cancer aggressiveness since it was shown to modulate migration, invasion and adhesion to the fibronectin of various cancer cells, including melanoma cells, with the regulation of metastasis-associated proteins MMP-2, TIMP-1, TIMP-2, STAT3 and IL-8." (PMID 34572799, 2021). "TIMP1 is MMP-independent and regulates cell development and apoptosis in various cancer cell types, including CRC." (PMID 34440739, 2021). "TIMP-1 and TIMP-2 play a crucial role in extracellular matrix (ECM) regulation, wound healing, pregnancy and cancer, and there is increasing evidence that they are immune-modulatory." (PMID 34638439, 2021). "The involvement of IGFBP1, TIMP1, SPP1, IGFBP3, and STC2 in mediating chemotherapy resistance in various cancers have been extensively studied." (PMID 34737677, 2021). "The majority of MMPs and TIMPs were mainly expressed in cancer cells at the invasive front (MMP-9: 97.3% of the tumors, MMP-11: 98.7%, MMP-14: 94.0%, TIMP-1: 86.7%, TIMP-2: 96.7%)." (PMID 33669393, 2021). "In contrast to TIMP-1 upregulation, there is overwhelming evidence for the occurrence of TIMP-3 silencing in multiple human cancers." (PMID 33419373, 2020). "Activated neutrophils, in turn, release TIMP-1-free MMP-9, which effectively aids cancer cells to breach blood vessel walls." (PMID 32630531, 2020). "TIMP-1 and TIMP-2 proteins have been found in EVs derived from cancer cells, bone marrow mesenchymal stem cells and also in pregnant women." (PMID 32610589, 2020). "Among the proteins differentially present in cancer vs. control were six common to both local and metastatic PDAC: Up—GDF15, TIMP1, and IL1RL1; Down—CCL22, APP, and CLEC1B." (PMID 33334063, 2020). "Several of the genes, including MMP1, MMP2, TIMP1 and HIF1A, are known cancer genes and facilitate stromal invasion." (PMID 31748560, 2019). "Despite the known role of TIMP-1 as being MMP inhibitors, it seems that the function of this protein is more complicated as some studies have shown that high TIMP levels tend toward cancer progression." (PMID 31582999, 2019). "This indicates that actein can upregulate the expression of inhibitors TIMP-1 and TIMP-2 but downregulate the expression of MMP-9 and MMP-2, thereby resulting in the suppression of cancer metastasis." (PMID 30618758, 2018). "Results for the expressions of TIMP1,2, upon 24 h actein treatment, demonstrated that actein significantly upregulated the expressions of TIMP1 and TIMP2, thereby resulting in reduced cancer progression and cancer cell invasion." (PMID 30618758, 2018). "Adipocytes in the omentum produce cytokines and chemokines, including highly secreted IL-6, IL-8, MCP-1, tissue inhibitor of metalloproteinases-1 (TIMP-1) and adiponectin, to promote cancer growth and omental metastases." (PMID 30042343, 2018). "In conclusion, our results suggested the important roles of ITGA2, FN1, ICAM1, TIMP1 and CDH2 in the progression of PTC via various cancer-related pathways." (PMID 30414611, 2018). "Cancer fibroblast and stromal cells had increased expression of MMP and MMP-related genes: MMP2, MMP11 and TIMP1." (PMID 30383866, 2018). "MGAT5 is considered to be an upstream regulator that affects many target proteins to promote cancer metastasis including MT1-MMP and TIMP-1." (PMID 28178684, 2017). "We next measured the effect of PA on mRNA and protein expression of MMP-2, MMP-9, TIMP-1, and TIMP-2 (which have critical roles in cancer cell migration and invasion) in HeLa cells by use of western blotting and RT-qPCR." (PMID 29267213, 2017). "In ovine adenocarcinomas, VEGFR2 and VEGFD mRNA were downregulated in cancers; MMP9, TIMP1 and FGFR2 mRNA were overexpressed as compared to normal lungs." (PMID 29137669, 2017).
cancer (continued). "IIF also induced differentiation in several cancer cell lines, inhibited MMP-2 and MMP-9 and increased expression of their inhibitors (TIMP-1 and TIMP-2)." (PMID 28465354, 2017). "TIMP1, another downstream molecule of IL6, has been reported to regulate the cancer cell survival, modulate the proteolytic activity in ECM, and negatively regulate the adipocyte differentiation." (PMID 28333977, 2017). "Their co-localization was significantly enhanced both on surface of and inside the carcinoma cells, although both normal breast epithelial cells and DCIS demonstrated co-localization of TIMP-1 and CD82." (PMID 28030805, 2017). "This is in keeping with elevated TIMP1 and TIMP2 expression in human cancers and their correlation with poorer prognosis." (PMID 26956475, 2016). "The aims of this study were to compare tissue levels of TIMP-1, COX-2 and MMP-7 in cancer, polyps and control groups to reveal their impact in carcinogenesis and metastasis." (PMID 29201696, 2015). "Significantly increased mRNA expression of MMP-2 and MMP-9 and decreased expression of TIMP-1 and TIMP-2 was observed in the cancer-induced group." (PMID 23599733, 2013). "In mucosal tissue from inflamed UC, collagen synthesis, pro-MMP-1, TIMP-1, pro-MMP-9 and IL-1β were significantly increased (p<0.03, all comparisons) compared to cancer control tissues." (PMID 23300643, 2012). "Elevated levels of TIMP-1 mRNA and TIMP-1 protein have been found in many types of cancer, including breast cancer." (PMID 22988515, 2012). "Several studies confirmed that high preoperative serum or plasma MMP-2, MMP-9 and mainly TIMP-1 antigen levels are strong prognostic factors for patients with CRC and their determination might be useful for identification of patients with higher risk for cancer recurrence." (PMID 23202950, 2012). "This concept represents a paradigm shift in the current view of TIMP-1/MT1-MMP interactions and functions during cancer development/progression." (PMID 22701711, 2012). "With such mind-set it was possible to solve the paradox why elevated systemic levels of tissue inhibitor of metalloproteinases-1 (TIMP-1), i.e., correlate with bad prognosis of many cancers." (PMID 22807917, 2012). "Several recent studies demonstrated that high preoperative serum or plasma MMP-2, MMP-9 and TIMP-1 antigen levels are strong predictive factors for poor prognosis in patients with CRC and their determination might be useful for identification of patients with higher risk for cancer recurrence." (PMID 23202950, 2012). "Microarray data were validated by rigorous statistical tests; however, we verified changes by RT-qPCR of TIMP-1 and PLZF, two genes expressed abnormally in other cancers." (PMID 21062482, 2010). "Constitutive expression and activity of MMPs increases the invasiveness of various types of cancer cells, and we have determined characterized the expression of MMP-2, MMP-9 and MMP-14 as well as TIMP-1 and TIMP-2 mRNA in EN-1078D cells, using RT-PCR." (PMID 17894888, 2007). "The results show that TIMP-1 is readily measured in plasma samples by ELISA and that increased levels of TIMP-1 are found in patients with advanced cancer." (PMID 10408859, 1999). "Oncogene addiction has been documented for KRAS mutants, whereby adenocarcinoma cell lines harboring KRAS mutations have been classified as KRAS-dependent or KRAS-independent.This study defines the relationship between KRAS addiction, TIMP-1 expression, and EMT in cancer progression." (PMID 41002380, 2025). "We focused on ENPEP, TIMP1, CD36, MARCKS, DAB2, CXCL14, miR-181b-5p, and miR-222-3p—genes and miRNAs previously implicated in cancer but not comprehensively analyzed in the context of EVs in BC." (PMID 40565366, 2025).
cancer (continued). "TIMP-1 and TIMP-2 can promote the proliferation and survival of cancer cells, such as TIMP-1, which has been shown to activate intracellular signaling pathways such as the phosphatidylinositol 3-kinase (PI3K)/Akt pathway, which promotes cell survival and proliferation." (PMID 40370880, 2025). "Among the identified prognostic genes, TIMP1, CXCL8, and MGP have been reported in various cancers." (PMID 40299331, 2025). "Complete CM-hUCESC significantly decreased migration of cancer cell line as compared with control (p < 0.0001, adjusted p value = 0.0007) and with CM-hUCESC lacking TIMP-1 and − 2 (IP TIMP-1/2) (p = 0.004, adjusted p value = 0.008)." (PMID 38664697, 2024). "Given the critical roles of MMPs and TIMPs in cancer biology, we hypothesized that MMP-9, MMP-14, TIMP-1, and MMP-2 could serve as prognostic biomarkers for regorafenib efficacy in mCRC patients." (PMID 39199626, 2024). "Conversely, necrosis was shown not to hinder but to enforce cancer progression and to increase proliferation (for example, through tissue inhibitor of metalloproteinases-1 (TIMP-1) and GCN2-ATF4 pathway) measured by Ki-67." (PMID 39736582, 2024). "In inverse co-culture at both time points and standard co-culture at 72 h 26 genes were mutually expressed, among them genes of the KEGG pathway Proteoglycans in cancer, like Fibronectin 1 (FN1), Hepatocyte Growth Factor (HGF), Epiregulin (EREG) and Tissue Inhibitor of Metalloproteinases 1 (TIMP1)." (PMID 39098880, 2024). "The interaction of TIMP1 protein’s C-terminal structural domain with tetraspanin CD63 stimulates conformational activation of integrin b1 and activates MAPK signaling, resulting in cancer." (PMID 36816016, 2023). "Further studies are warranted to establish whether TIMP‐1 and CD74 function as tropism factors for cancer cells and whether targeting their interaction would result in a novel therapeutic treatment for patients." (PMID 37081824, 2023). "In line with this, we showed that TIMP-1-mediated activation of both signaling pathways is not restricted to cancer cells, but also expands to immune cells, particularly primary monocytes." (PMID 37508563, 2023). "For example, the levels of plasma TIMP-1 can be used as a biomarker, as this soluble tumor-derived secreted factor appears to be the main player in determining the propensity for liver PMN formation in various cancers." (PMID 37350937, 2023). "However, in the case of combined Selumetinib- and Trametinib-resistant cancers, FN1 and CD44 were down-regulated; TIMP1 and SNAI2 were down-regulated only in Selumetinib-resistant ones; while SPARC was down-regulated in the case of Trametinib-resistant cancer." (PMID 35534592, 2022). "From our big data studies validated with independent datasets, protein-coding hub genes FN1, CD44, TIMP1, SNAI2, and SPARC were found significantly enriched in signal transduction, proteolysis, cell adhesion and proteoglycans pathways in cancer as well as the PI3K/Akt-signaling pathway." (PMID 35534592, 2022). "TIMP-1 forms a complex with CD63 and integrin β1 on collagen, and then activates Src and RhoA, resulting in F-actin assembly that inactivates LATS1/2 and activates YAP/TAZ in many types of cancer cell lines, including HNSCC." (PMID 36294681, 2022). "This article reviewed the characteristics and functions performed individually by TIMP1, CD63, and β1-integrin, the roles of the TIMP-1/CD63/β1-integrin complex, both in a physiological context and in cancer, and the regulatory mechanisms involved in its assembly." (PMID 34502227, 2021). "Among them, ITGB5 is highly expressed cancers, TIMP1, and TMEM176B are lowly expressed in cancers." (PMID 34109215, 2021). "TIMP2, but not TIMP1, secreted by monocyte-like cells, is a potent suppressor of invadopodium formation in breast and pancreatic cancers." (PMID 34638439, 2021). "ITGB5, TIMP1, and TMEM176B are abnormally expressed in several human cancers." (PMID 34109215, 2021).